ATG5 (autophagy related 5)
Diseases named in the same sentence as ATG5 in open-access papers (continued):
Sharing a sentence is not in itself a finding about the gene and the disease.
medullary carcinoma (2 papers, 2021 to 2022). "In radiation-induced medullary carcinoma in 4W rats, the expression of Cdkn2a and Cxcr4 increased, whereas that of seven autophagy regulatory genes (Dapk1, Eif2ak3, Gaa, Hgs, Mapkl4, Mapt, and Pim2) and five autophagy machinery components (Atg4b, Atg5, Gabarapl2, Rab24, and Wipi1) decreased." (PMID 34580369, 2021).
metastatic melanoma (2 papers, 2021 to 2023). A melanoma that has spread from its primary site to another anatomic site. "We found that ATG5 and ATG7 are downregulated in primary and metastatic melanomas as compared to benign nevi and that patients with high levels of ATG5 and ATG7 in their tumors exhibited a better overall survival." (PMID 34458153, 2021). "Interestingly, the levels of ATG5 were similarly decreased in both primary and metastatic melanomas." (PMID 34458153, 2021). "In addition to our previous study where we demonstrated decreased expression of Beclin-1 in metastatic melanomas, we show here that the expression of two more ATG proteins, ATG5 and ATG7, are reduced in primary and metastatic melanomas compared to benign nevi." (PMID 34458153, 2021).
Mycobacterium infection (2 papers, 2017 to 2020). Infections with bacteria of the genus Mycobacterium. "Mice with an Atg5 (autophagy-related protein 5) deletion in the myeloid lineage are more susceptible to mycobacterium infection." (PMID 28529930, 2017).
myeloid leukaemia (2 papers, 2017 to 2022). "Similarly, in murine myeloid leukaemia, ablation of ATG5, the key autophagy protein, could increase apoptosis of differentiated malignant myeloid cells and prolong the survival of MLL‐AF9‐driven AML mice." (PMID 36124714, 2022).
neuromyelitis optica (2 papers, 2018 to 2022). A rare inflammatory disease of the central nervous system characterized mainly by attacks of uni- or bilateral optic neuritis (ON) and acute myelitis. "Neuromyelitis optica (NMO) is a CNS autoimmune disease that is associated with ATG5." (PMID 30386331, 2018).
papillary thyroid cancer (2 papers, 2022 to 2023). "Thus, miR-125b are able to regulate transcription and translation of the ATG5 protein, mediating the resistance to therapy in papillary thyroid cancer." (PMID 36980957, 2023). "Finally, prognostic analysis of MIEAP and ATG5 expression levels using the Human Protein Atlas and TCGA dataset revealed that these two molecules are not prognostic in papillary thyroid cancers (PTCs) (data not shown)." (PMID 36187114, 2022).
prostate tumors (2 papers, 2019 to 2024). "At the mRNA level, TCGA data reveal that the average expression of full-length ATG5 mRNA is increased in prostate tumours compared to normal prostatic tissue." (PMID 38910881, 2024). "Of relevance, two reports have indicated that ATG5 protein is frequently highly overexpressed in prostate tumours compared to normal prostate tissue." (PMID 38910881, 2024).
Sjögren Syndrome (2 papers, 2021). "Although clinical trials with large sample sizes would be useful to confirm these findings, ATG5 is expected to serve as a disease-specific diagnostic marker of Sjögren's syndrome DED." (PMID 34970573, 2021). "In a previous study, autophagy occurred in the lacrimal glands of the mouse model of DED; a significant colocalization of LC3-phosphatidylethanolamine conjugate (LC3B) and autophagy-related gene 5 (ATG5) was detected in the salivary glands of patients with primary Sjögren's syndrome." (PMID 34970573, 2021). "Compared to the controls, ATG5 levels in tear and conjunctival epithelial cells were upregulated in Sjögren's syndrome DED but not in non-Sjögren's syndrome DED." (PMID 34970573, 2021).
squamous cell carcinoma (2 papers, 2016 to 2018). A carcinoma arising from squamous epithelial cells. "We found a sustained increase in Bcl-2, Beclin-1, ATG5,LC-3 and p-AktSer473 associated with decreased expression of Bax and cleaved caspase-3 during progression of normal epithelium through hyperplasia, dysplasia and well-differentiated squamous cell carcinoma of the hamster buccal pouch." (PMID 30352996, 2018).
thyroid (2 papers, 2014 to 2022). "To investigate the role of MIEAP and ATG5 in thyroid carcinogenesis, we prepared Brafthyr–V600E, MieapKO/KO, Atg5thyr–KO/KO, Brafthyr–V600E,MieapKO/KO, and Brafthyr–V600E,Atg5thyr–KO/KO mice." (PMID 36187114, 2022).
toxoplasmosis (2 papers, 2010 to 2026). A parasitic disease contracted by the ingestion or fetal transmission of toxoplasma gondii. "Collectively, ATG5 may have mediated premature parasite egress and mitochondrial damage, demonstrating its antiparasitic activity and therapeutic potential in controlling toxoplasmosis." (PMID 42253334, 2026).
uveal melanoma (2 papers, 2020 to 2024). A melanoma derived from melanocytes of the uveal tract. "Knock down of Beclin1 or ATG5, or expression of an activated form of mTOR, significantly reduced uveal melanoma cell killing." (PMID 38758815, 2024).
acute lymphoblastic leukemia (1 paper, 2023). Leukemia with an acute onset, characterized by the presence of lymphoblasts in the bone marrow and the peripheral blood. "In contrast, a recent study found that an Egyptian cohort with newly diagnosed acute lymphoblastic leukemia (ALL) had considerably greater levels of ATG5 expression." (PMID 37180758, 2023).
age-related macular degeneration (1 paper, 2023). Age-related loss of vision in the central portion of the retina (macula), secondary to retinal degeneration. "Knockout of the Atg5 and Atg7 in mice RPE results in insufficient autophagy and age-related macular degeneration-like phenotype in aged mice." (PMID 37936170, 2023).
asbestosis (1 paper, 2023). A lung disorder caused by inhalation of asbestos fibers. "Indeed, high levels of ATG5, miR-222 and mesothelin were associated with the presence of benign ARDs, such as asbestosis and/or pleural plaques." (PMID 37095543, 2023).
benign prostate hyperplasia (1 paper, 2022). "Besides, some scholars have discovered that the expression level of Atg5 is higher in benign prostatic carcinoma tissues than in benign prostate hyperplasia tissues." (PMID 35720225, 2022).
bladder tumor (1 paper, 2026). "Amiodarone-induced autophagy activity suppressed bladder tumor formation, whereas silencing Atg5 expression reversed the suppression." (PMID 41574655, 2026).
blastoma (1 paper, 2015). A malignant neoplasm composed of undifferentiated cells. "While ATG3, ATG5, ATG7 and ATG12 are upregulated to induce autophagy in neuro-blastoma cells when G9a is inhibited." (PMID 26397365, 2015).
brain cancer (1 paper, 2020). A primary or metastatic malignant neoplasm affecting the brain. "Furthermore, our Western blot analysis showed an up-regulation of LC3B, which is a marker for the formation of autophagic vesicles, Beclin-1 and ATG5 in U-87 MG, U-251 MG, and Daoy brain cancer cells." (PMID 32971907, 2020).
brain infarct (1 paper, 2022). "Firstly, we revealed that perinatal nicotine exposure enhanced miR-181a in the neonatal brain while enhancement of miR-181a activity with its mimic suppressed ATG5 expression and increased H/I-induced brain infarct size in neonatal pups." (PMID 35805891, 2022). "In addition to increase brain infarct sizes, treatment with miR-181a mimic (100 pmol) significantly decreased the levels of ATG5 protein in the neonatal brain (p < 0.0001)." (PMID 35805891, 2022). "Secondly, we further verified that inhibition of miR-181a with LNA-miR-181a antisense reduced perinatal nicotine-mediated miR-181a overexpression and eliminated the differences of ATG5 expression and H/I-induced brain infarct size between nicotine exposed and saline control groups." (PMID 35805891, 2022).
cervical adenocarcinoma (1 paper, 2021). An adenocarcinoma arising from the cervical epithelium. "For cervical adenocarcinoma, due to the limited sample size of patients included in the analysis, the p-value of the km survival curve is not significant, but patients with ATG5 down-expression showed a trend towards a longer survival with no death during the follow-up times." (PMID 34901004, 2021).
chlamydia infection (1 paper, 2024). "Furthermore, Atg5 knockdown promotes the secretion of proinflammatory cytokines IL-1β and IFN-γ in C. trachomatis-infected cells, suggesting an anti-inflammatory role for Atg5 in the autophagy induction during chlamydia infection." (PMID 39310786, 2024).
chondrosarcoma (1 paper, 2016). A malignant cartilaginous matrix-producing mesenchymal neoplasm arising from the bone and soft tissue. "Western blot data confirmed that bortezomib increased the protein expression of the autophagy related proteins Atg5/12 and Beclin in both chondrosarcoma cell lines." (PMID 27978543, 2016). "Therefore, we monitored the expression of the autophagy-associated proteins Atg5/12, Beclin, and LC3I-II in chondrosarcoma cells following treatment with bortezomib." (PMID 27978543, 2016).
chordoma (1 paper, 2021). Chordomas are rare malignant tumors arising from embryonic remnants of the notochord in axial skeleton. "We then investigated potential associations between ATG5 expression and the clinical features and prognoses of the 84 chordoma patients." (PMID 34668612, 2021). "Mechanistically, SMARCB1 binds directly to the ATG5 promoter and transcriptionally regulates its expression, which subsequently regulates autophagy and the malignant phenotype of chordoma." (PMID 34668612, 2021). "As a result, higher ATG5 expression was observed in recurrent chordoma compared with corresponding primary tumours, suggesting an oncogenic role of ATG5 in chordoma." (PMID 34668612, 2021). "Consistent with prior observations, we found positive expression of ATG5, a vital ATG during autophagy, in chordoma, especially recurrent chordoma, and identified ATG5 as a novel adverse prognostic factor of chordoma patients." (PMID 34668612, 2021). "Together, these results indicated that ATG5‐mediated autophagy was essential for the malignant phenotype of SMARCB1 knockdown chordoma cells." (PMID 34668612, 2021). "To determine whether ATG5 participates in the tumour suppressor role of SMARCB1 in chordoma, we examined the effect of ATG5 knockdown in UM‐Chor1 and MUG‐Chor1 cells with SMARCB1 knockdown." (PMID 34668612, 2021). "We next analysed the expression of ATG5 in chordoma tissues by IHC." (PMID 34668612, 2021). "Our finding highlights that the SMARCB1/ATG5 axis is a promising therapeutic target for chordoma and autophagy inhibitors may be effective agents for chordoma treatment." (PMID 34668612, 2021). "Additionally, our in vitro data suggested impairments of proliferation, migration and invasion of chordoma cells after blocking autophagy by ATG5 siRNA or autophagy inhibitor CQ, revealing the tumour promotive effect of autophagy in chordoma." (PMID 34668612, 2021). "Taken together, our results revealed that the SMARCB1/ATG5 axis is a promising therapeutic target for chordoma and autophagy inhibitors may be effective agents for chordoma treatment." (PMID 34668612, 2021). "Additionally, no previous study has investigated the expression, prognostic role or potential upstream regulators of ATG5 in chordoma." (PMID 34668612, 2021). "Moreover, we identified ATG5 as a direct downstream target of SMARCB1 and revealed the association between autophagy and SMARCB1 in chordoma." (PMID 34668612, 2021). "Moreover, high ATG5 expression was observed in recurrent chordoma patients, which independently correlated with adverse outcomes." (PMID 34668612, 2021). "In addition, the ATG5 expression in chordoma tissue was assessed using immunohistochemistry and correlated with patient survival." (PMID 34668612, 2021). "Moreover, ChIP sequencing and GO analysis revealed that autophagy may be involved in the effect of SMARCB1 on chordoma cells and identified ATG5 as a novel transcriptional target of SMARCB1." (PMID 34668612, 2021). "Moreover, multivariable Cox analysis identified that high ATG5 could independently predict an adverse prognosis of chordoma patients." (PMID 34668612, 2021). "We also found augmentation of ATG5 expression in SMARCB1 knockdown cells and impaired ATG5 expression in SMARCB1‐overexpressing chordoma cells." (PMID 34668612, 2021). "Our results are in favour of the speculation that compared with SMARCB1 positive chordoma, the autophagy is enhanced in SMARCB1 negative chordoma due to the loss of SMARCB1 and subsequently transcriptional activation of ATG5, contributing to the malignant phenotype and adverse survival." (PMID 34668612, 2021).
chronic eosinophilic leukemia (1 paper, 2021). "Moreover, the differentiation potential of Atg5-knockout eosinophil precursors was tested under pathologic conditions, employing an established mouse model of chronic eosinophilic leukemia (CEL)." (PMID 34019141, 2021).
chronic obstructive pulmonary disease (1 paper, 2012). A chronic and progressive lung disorder characterized by the loss of elasticity of the bronchial tree and the air sacs, destruction of the air sacs wall, thickening of the bronchial wall, and mucous accumulation in the bronchial tree. "While there have been no previous studies investigating Atg5 expression in asthmatics, there is evidence of increased expression of autophagic proteins, including Atg5, in lung tissue from patients with chronic obstructive pulmonary disease." (PMID 22536318, 2012).
Cirrhosis (1 paper, 2022). A chronic disorder of the liver in which liver tissue becomes scarred and is partially replaced by regenerative nodules and fibrotic tissue resulting in loss of liver function. "LncRNA SNHG1 or SMURF1 silencing or miR-15a overexpression promoted differentiation of BMSCs into HLCs and repressed cirrhosis of mice by upregulating ATG5 and Wnt5a via UVRAG." (PMID 35194023, 2022). "Conclusively, lncRNA SNHG1 silencing might facilitate HLC differentiation from mouse BMSCs and alleviate cirrhosis via the miR-15a/SMURF1/UVRAG/ATG5/Wnt5a axis." (PMID 35194023, 2022). "Therefore, our work was designed to figure out impacts of lncRNA SNHG1 on cirrhosis by orchestrating HLC differentiation of BMSCs via miR-15a/SMURF1/UVRAG/ATG5/Wnt5a axis." (PMID 35194023, 2022). "Another critical finding in our study was that overexpressed UVRAG promoted ATG5/Wnt5a activation to decrease HLC differentiation of BMSCs, thus alleviating cirrhosis." (PMID 35194023, 2022).
colonic adenoma (1 paper, 2025). "Similarly, ATG5-silenced human colonic adenoma cells show significantly elevated IL-1β production under LPS stimulation." (PMID 41463800, 2025).
dementia with Lewy bodies (1 paper, 2021). "Impaired autophagy in neurons through genetic disruption of MAP1LC3A/B along with ATG5/ATG7 induced neuropathologic features in dementia with Lewy bodies (DLB) patients." (PMID 33419148, 2021).
dilatation (1 paper, 2023). "Of great significance, the deleterious effect of autophagy inhibition in PO-evoked systolic HF was elegantly demonstrated in a prior publication, in which Atg5 deficient mice exhibited LV dilatation and severe systolic dysfunction early after PO induction." (PMID 37752166, 2023).
Duchenne muscular dystrophy (1 paper, 2025). Duchenne muscular dystrophy (DMD) is a neuromuscular disease characterized by rapidly progressive muscle weakness and wasting due to degeneration of skeletal, smooth and cardiac muscle. "Similarly, prior research has reported that Ectoine administration effectively enhanced autophagic efficiency in a mouse model of Duchenne muscular dystrophy (DMD) by upregulating the autophagic proteins LC3 and ATG5." (PMID 41359280, 2025).
eosinophilia (1 paper, 2019). "A consistent observation was noted in a recent study with the same mouse model, in which autophagy inhibition by 3-methyladenine or ATG5 shRNA treatment reduced airway responsiveness, eosinophilia, and inflammation." (PMID 30729138, 2019).
fungal infection (1 paper, 2025). "In the context of fungal infection, ATG5 and ATG16L1 contribute to plasma membrane repair through lysosomal exocytosis, safeguarding epithelial cells against Candida albicans (C. albicans)." (PMID 40529614, 2025).
gastrointestinal stromal tumor (1 paper, 2025). "For example, USP13 interacts with and stabilizes ATG5 by removing the K48-linked polyubiquitin chains from ATG5, which induces prosurvival autophagy in gastrointestinal stromal tumors." (PMID 41004574, 2025).
Hepatomegaly (1 paper, 2022). Abnormally increased size of the liver. "Hepatomegaly in Atg5 CD11cKO mice could not be attributed to total body weight gain after HFD, as the liver weight to total body weight ratio was significantly higher in Atg5 CD11cKO mice when compared to WT controls." (PMID 35301333, 2022).
hypertriglyceridemia (1 paper, 2022). A laboratory test result indicating elevated triglyceride concentration in the blood. "Neutralizing the IL-23 pathway prevented hepatic hypertriglyceridemia in both control and Atg5 CD11cKO mice." (PMID 35301333, 2022).
IgA nephropathy (1 paper, 2025). "Furtherly, we examined the expression of ATG5 in kidney biopsies obtained from CKD patients diagnosed with IgA nephropathy." (PMID 40047327, 2025).
ileitis (1 paper, 2022). "In mouse models, decreased expression levels of Atg5, Atg7, or Atg4B generated abnormal Paneth cell functions, and in CD-like ileitis, deficiency of Atg16L1 also altered Paneth cell morphology." (PMID 35408838, 2022). "Complete knockout of Atg3, Atg5, Atg7, or Atg16L1 is lethal in mice, and impairment of either Atg7 or Atg16L1 results in severe CD-like transmural ileitis." (PMID 35408838, 2022).
Insulin resistance (1 paper, 2022). Increased resistance towards insulin, that is, diminished effectiveness of insulin in reducing blood glucose levels. "Similarly, therapeutic anti-IL-23 treatment in Atg5 CD11c deficient mice proves that established insulin resistance and NAFLD can be reversed via this approach." (PMID 35301333, 2022). "Thus far, we observed that Atg5 deletion in CD11c+ cells induced increased insulin resistance and NAFLD development and is associated with increased IL-23 production." (PMID 35301333, 2022). "Overall, this data confirms that deletion of Atg5 in CD11c+ cells induces IL-23 activation, which in turn contributes to the development of insulin resistance and NAFLD." (PMID 35301333, 2022). "Altogether, these results suggest that the deletion of Atg5 in CD11c+ cells activates IL-23 secretion likely in a p38/ NF-κB-dependent manner, inducing insulin resistance and NAFLD development." (PMID 35301333, 2022). "By using a blocking antibody against IL-23, we were able to prevent the development of insulin resistance and NAFLD in Atg5 CD11cKO mice, suggesting that autophagy deletion causes IL-23 induction, resulting in metabolic derangements contributing to these distinct but related conditions." (PMID 35301333, 2022). "Here, we analyze the activity of autophagy in hepatic myeloid cells using a model of Atg5 deletion in CD11c+ cells, Atg5 CD11cKO mice which develop NAFLD and insulin resistance when administered a high-fat diet." (PMID 35301333, 2022). "Atg5 CD11cKO and control mice were fed HFD for 8 weeks to establish insulin resistance and induce NAFLD." (PMID 35301333, 2022).
intestinal obstruction (1 paper, 2024). Blockage of the normal flow of the intestinal contents within the bowel. "Down-regulation of Atg1 or Atg12 promoted intestinal excretion and mitigated the intestinal obstruction, whereas down-regulation of Atg5, or Atg7 hindered the activities of eating or defecating." (PMID 38900277, 2024). "Consistently, the groups with severe intestinal obstruction in the context of trpQ78 (that is, Atg5, Atg7 RNAi) displayed more severe apoptosis, while the Atg1 and Atg12 RNAi groups, which had mitigated intestinal obstruction, had reduced apoptosis levels." (PMID 38900277, 2024).
intestinal tumor (1 paper, 2018). "Experimental studies on mice models have shown that heterozygous deletion of ATG5 is involved in intestinal tumor growth and sensitizes tumor cells to chemotherapy." (PMID 30374741, 2018).